MIR320B2 (microRNA 320b-2)
Synonyms: hsa-mir-320b-2; formerly MIRN320B2
Gene: MicroRNA gene on chromosome 1 (224,257,004 to 224,257,141, reverse strand). Ensembl gene ENSG00000221406.
Gene Ontology:
Biological process: cellular response to glucose stimulus; long-term synaptic potentiation; miRNA-mediated post-transcriptional gene silencing; negative regulation of gene expression; positive regulation of stem cell proliferation
Cellular component: RISC complex
Homologues: Orthologues: chimpanzee ptr-mir-320b-2 (100% identical), tropical clawed frog xtr-mir-320 (25% identical). Paralogues in human: MIR320A (41% identical), MIR320B1 (37% identical), MIR320C2 (31% identical), MIR320E (31% identical), MIR320D2 (28% identical).